PALB2 (partner and localizer of BRCA2)
Diseases named in the same sentence as PALB2 in open-access papers (continued):
Sharing a sentence is not in itself a finding about the gene and the disease.
breast cancer (continued). "A higher risk of developing breast cancer was estimated in PALB2 mutation carriers, which was 9.1-fold compared to non-carriers in the UK." (PMID 34439348, 2021). "Collectively, our results suggest that elevated ROS rather than DNA damage may be responsible for the increased apoptosis of the Brca1;Palb2 double KO MECs and therefore may contribute to the reduced mammary tumor formation in these mice." (PMID 33893322, 2021). "Here we report a hitherto unknown PALB2 5.6-kilobase deletion involving exons 5 and 6 and the neighboring introns in a breast cancer patient." (PMID 33718150, 2021). "PALB2 and CHEK2 are clear breast cancer susceptibility genes." (PMID 34461861, 2021). "Upon extending our investigation to PALB2, the third high-penetrance breast cancer gene identified thus far, we reported that also the c.1027C>T PV has been exclusively identified in breast cancer patients—and to a significantly lower extent, in healthy individuals—from Bergamo." (PMID 33573335, 2021). "Female breast cancer patients who carried one of the two Polish PALB2 founder mutations had a 10-year survival of 48%, compared to 75% for patients with breast cancer without a PALB2 mutation (HR = 2.27, 95% CI 1.64–3.15; p < 0.0001)." (PMID 34461861, 2021). "It is speculated that the increased incidence of breast cancer in women who carry BRCA1, BRCA2 or PALB2 germline mutations is due to deficiencies in DNA damage repair." (PMID 35187501, 2021). "EC has been reported in relatives of breast cancer patients known to carry loss of function variants in PALB2, but carrier status was not confirmed." (PMID 33917078, 2021). "To understand the mechanism underlying the delayed mammary tumor development in B1P2p mice, we asked whether combined loss of BRCA1 and PALB2 would cause synthetic lethality in MECs, thereby reducing their overall tumorigenic potential." (PMID 33893322, 2021). "To date, no effective therapeutic strategies have been devised for PALB2 mutation-carrying breast cancer patients, despite a few case studies suggesting the use of platinum-based chemotherapies in the metastatic setting." (PMID 34439348, 2021). "Grade 3 ER-positive HER2-negative, grade 3 and triple negative (TN) tumors were enriched in cases with PALB2 PGVs compared with all breast cancers known to our service (respectively: 15/43, 254/1,843, P = 0.0005; 28/37, 562/1,381, P = 0.0001; 12/43, 204/1,639, P < 0.0001)." (PMID 34113003, 2021). "The nearly identical timing of the “first wave” of mammary tumor development suggests that BRCA1, BRCA2, and PALB2 may be functionally equivalent in mammary tumor suppression." (PMID 33893322, 2021). "In contrast, a first diagnosis of TNBC rather than any other breast cancer subtype was associated with BRCA2 or PALB2 for AA patients, but not for EA patients." (PMID 33479248, 2021). "The authors determined the frequency of PALB2 monoallelic truncating variants in a familial breast cancer cohort negative for BRCA mutations (10/923, 1.1%), which was far more common than in controls (0/1,084, 0%; p = 0.0004)." (PMID 32185139, 2020).
breast cancer (continued). "Hence, a comprehensive understanding of the biological functions of PALB2 is vital for breast cancer management and precision medicine." (PMID 32185139, 2020). "In our study, germline PALB2 heterozygous mutations were detected in non-familial breast cancer patients." (PMID 33193564, 2020). "Additionally, pathogenic alterations in PALB2, ATM, CHEK2, and NBN are correlated with an increased risk for breast cancer and/or other cancers, whereas other genes such as BRIP1, RAD51C, and RAD51D are associated with an increased ovarian cancer risk." (PMID 32733558, 2020). "In this study, the 10-year survival rate for female breast cancer patients with a PALB2 mutation was 48.0% (95% CI, 36.5–63.2), significantly lower than that for PALB2 mutation-negative female breast cancer patients (74.7%; 95% CI, 73.5–75.8)." (PMID 32185139, 2020). "Briefly, in 4 families, the mutant and wildtype alleles showed exact concordance with breast cancer occurrence for variants including PALB2 and BLM, but the remaining 9 families did not perfectly match with the presence of breast or ovarian disease." (PMID 32566746, 2020). "For both PALB2 and CHEK2, a high PRS further increased the breast cancer risk." (PMID 33318493, 2020). "That PRS modifies the risk in PALB2 and CHEK2 mutation carriers supports previous findings suggesting that common genetic variation at least partly explains the widely observed incomplete penetrance of mutations in breast cancer susceptibility genes." (PMID 33318493, 2020). "A combination of breast cancer PRS in the top decile and a mutation in the CHEK2 variant increased the lifetime risk to 59% – a risk comparable to that seen in PALB2 mutation carriers – whereas those with a PRS in the bottom decile had a risk similar to the population level." (PMID 33318493, 2020). "The identified breast cancer susceptibility genes in the FA pathway, including BRCA1, BRCA2, BRIP1, PALB2, and RAD51C, are essential genes involved in HR, the error-free pathway for DSB repair during physiological cell cycle progression, which repairs replication-associated DNA damage." (PMID 32300589, 2020). "Nonetheless, the fact that roles other than in HR (i.e., in replication fork stability/recovery) for all three major breast cancer susceptibility genes (BRCA1, BRCA2 and PALB2) have been described, complicates the interpretation of VUS in these genes and their association with cancer risk." (PMID 33195396, 2020). "Comparisons with non-cancer east-Asian populations and European familial breast cancer cohorts revealed significant enrichment of PALB2, BARD1, and BLM mutations." (PMID 32566746, 2020). "Both PALB2 and CHEK2 conferred considerably elevated risk for breast cancer." (PMID 33318493, 2020). "Initial clinical testing (BRCA1, BRCA2 and PALB2) in a 40-year-old female with unilateral breast cancer did not detect any pathogenic variants." (PMID 32884827, 2020). "While truncating variants in BRCA2 and PALB2 confer a substantial risk of breast cancer, our study suggests that truncating FANCC variants do not confer a comparable risk." (PMID 31467304, 2019).
breast cancer (continued). "Conversely, 8/24 PALB2-associated breast cancers included in this study lacked bi-allelic PALB2 inactivation and 2/16 PALB2-associated breast cancers sequenced by WES lacked both bi-allelic PALB2 inactivation and genomic features of HRD." (PMID 31428676, 2019). "PALB2 mutant genes were also found in European families with a history of breast cancer." (PMID 30975222, 2019). "All PALB2-associated breast cancers were invasive ductal carcinomas of no special type, and one, 12, and eleven cases were of histologic grades 1, 2, and 3, respectively." (PMID 31428676, 2019). "Two of the 12 PALB2-associated breast cancers analyzed by WES lacked both evidence of bi-allelic PALB2 inactivation and genomic features of HRD." (PMID 31428676, 2019). "For example, 60.13% of the ‘Gene: BRCA1 or BRCA2’ subpopulation had breast cancer before age 50 years, with a mean onset age at 46.80 ± 11.87 years compared to 64% of the ‘Gene: PALB2’ subpopulation that had breast cancer before age 50 years, with a mean onset age at 49.20 ± 8.50 years." (PMID 30759220, 2019). "Moreover, LST score, mutational signature 3, NtAI score and Myriad score detected bi-allelic inactivation of PALB2 and of BRCA1/BRCA2 in PALB2-associated breast cancers and in BRCA1/2-associated breast cancers, respectively, with comparable accuracy." (PMID 31428676, 2019). "Hence, we genotyped the PALB2:p.Pro1088Ser in 126 familial and 477 consecutive breast cancer cases, and 1,074 controls all born in the province of Bergamo but no additional carriers were found." (PMID 30410870, 2018). "Finally, we demonstrated that the RAD51 assay is feasible in formalin‐fixed paraffin‐embedded (FFPE) routine breast cancer samples and accurately classified as HRR‐deficient all the PALB2‐related tumors." (PMID 30377213, 2018). "In conclusion, these results suggest that PALB2 expression levels may serve as a novel prognostic factor for breast cancer patients." (PMID 29321957, 2018). "These genes included PALB2, BRCA2, and ATM, which are associated with breast cancer risk." (PMID 29706558, 2018). "As EMT regulators such as Slug, Snail and NF‐κB are important regulators for E‐cadherin, we evaluated the expression level of E‐cadherin and the transcription factors and found that PALB2 may affect the EMT of breast cancer cells." (PMID 29321957, 2018). "Little is known about PALB2 gene expression in sporadic breast cancer." (PMID 29321957, 2018). "The roles of PALB2 in breast cancer progression need further investigation." (PMID 29321957, 2018). "Moreover, since many of the recruited high risk patients tested negative for BRCA1/2 mutations, it is plausible to take advantage of the collected DNA samples and test for mutations in other breast cancer susceptibility genes, e.g. CHEK2, PALB2 and BRIP1." (PMID 29409476, 2018). "In the current study, we aimed to characterize functionally the two rare missense variants, PALB2:c.3262C>T (p.Pro1088Ser) and BRCA2:c.91T>G (p.Trp31Gly), that were initially identified in breast cancer families and that are located in the protein interaction domains." (PMID 30410870, 2018). "Furthermore, variants of CHEK2 (1100delC, IVS2 + 1G/A, del5395bp, and I157T), PALB2 (509_510delGA and 172_175delTTGT) and RECQL (c.1667_1667 + 3delAGTA) are also associated with breast cancer in the Polish population." (PMID 29678143, 2018). "In the present study, PALB2 was found to participate in human breast cancer progression." (PMID 29321957, 2018).
breast cancer (continued). "Various studies have been performed to evaluate the biological roles of PALB2 in genome stability and the DNA repair process, but whether PALB2 participates in the progression of breast cancer is unknown." (PMID 29321957, 2018). "A total of 117 breast carcinoma specimens were available for analysis of PALB2 IHC staining." (PMID 29321957, 2018). "It is known that up to 10% of breast cancers may be caused by inherited mutations in breast cancer susceptibility genes, including BRCA1/2 and PALB2." (PMID 29023372, 2017). "Particularly in breast cancer, the majority of the known susceptibility genes encode proteins with integral roles in DNA damage response (DDR), including the two major ones BRCA1 and BRCA2, and a number of others, such as PALB2, ATM and CHEK23–5." (PMID 28386063, 2017). "Given the relatively low frequency of RAD51C, RAD51D, FANCM, and PALB2 mutations among unselected female breast cancer patients, the absence of the studied mutations in the MBC series was not unexpected." (PMID 28874143, 2017). "In this study, we did not detect the RAD51C, RAD51D, FANCM, or PALB2 mutations among male breast cancer patients." (PMID 28874143, 2017). "Carriers of deleterious variants in either ATM, CHEK2, PALB2 or NBN are typically counseled for their risk of breast cancer, but not ovarian cancer risk despite associations in current literature." (PMID 28591191, 2017). "This was not considered appropriate for the associations with breast cancer risk of PALB2 c.1592delT, c.3113G>A and ATM c.7271T>G because these associations had previously been reported; our aim was to more precisely estimate the associated relative risks." (PMID 27595995, 2016). "Consistent with previous reports,5–7, 9, 11–13PALB2 c.3113G>A (p.Trp1038*), PALB2 c.1592delT (p.Leu531Cysfs) and ATM c.7271T>G (p.Val2424Gly) were found to be associated with substantially increased risk of breast cancer all with associated relative risk estimates of 3.44 or greater." (PMID 27595995, 2016). "They sequenced PALB2 in 1084 controls and 923 cases with a family history of breast cancer but no BRCA mutation." (PMID 27716388, 2016). "The moderate-risk genes—CHEK2, ATM, and PALB2—had positive yields of 2.0% (n = 66), 1.0% (n = 33), and 0.8% (n = 25), respectively, among the 3,315 women with breast cancer and no previous testing." (PMID 26681312, 2016). "The risk of developing breast cancer is more than four times higher in PALB2 mutation carriers compared to non-carriers." (PMID 26843898, 2016). "PALB2 alone accounted for 7.6% (25/330) of all positive findings among female patients with breast cancer without previous testing, which draws attention to its relevance in breast cancer genetic testing." (PMID 26681312, 2016). "PALB2, a partner and localizer of BRCA2, is another gene commonly associated with breast cancer." (PMID 30460281, 2016). "Among those who develop breast cancer, the risk of dying at ten years is two times higher for PALB2 mutation carriers compared to non-carriers (HR = 2.3; p < 0.0001)." (PMID 26843898, 2016). "Further studies are required to test if women who carry PALB2 mutations are at increased risk of death from breast cancer compared to non-carriers." (PMID 27099641, 2016). "Interestingly, the N-terminal region of PALB2 binds to BRCA1, a breast cancer associated protein involved in DNA damage response and repair, and this interaction is impaired in G1 through the ubiquitination of PALB2." (PMID 27490902, 2016). "PALB2 mutations account for a small, but not negligible, proportion of patients with hereditary predisposition to breast cancer in the Xinjing region of China." (PMID 26489409, 2015).
breast cancer (continued). "The current study is the first study performing mutation analyses in BRCA1, BRCA2 and PALB2 and determining the frequency of CHEK2 c.1100delC in triple negative and/or premenopausal breast cancer patients in South Africa through both next generation sequencing and large rearrangement testing." (PMID 26577449, 2015). "Therefore it is important to continue to amass the necessary data to support the implementation of whole gene testing of PALB2 in breast cancer families." (PMID 26283626, 2015). "A recent report has revealed that women with mutations in the PALB2 gene were more than nine times as likely to develop breast cancer compared to those without." (PMID 26489409, 2015). "Rahman and colleagues investigated a cohort of 923 breast cancer cases of which 10 individuals presented with mono-allelic truncating PALB2 mutations, while a set of 1,084 controls harboured no truncating mutations." (PMID 24949998, 2014). "The known high risk susceptibility genes for breast cancer, e.g. BRCA1, BRCA2, ATM, and PALB2, are responsible for approximately 20% of the hereditary cases, but several unknown breast cancer–predisposing genetic factors still exist." (PMID 25029565, 2014). "While some families with PALB2 stop mutations were noted to have a history of breast and pancreatic cancer, breast cancer was not seen in all families." (PMID 24624093, 2014). "Not surprisingly, PALB2 has emerged in the last few years as an important breast cancer susceptibility gene in its own right." (PMID 25225577, 2014). "When we consider truncating mutations alone, as Rahman and colleagues did in relation to breast cancer susceptibility, the data overall are not strongly supportive of PALB2 being a melanoma susceptibility gene." (PMID 24949998, 2014). "Segregation analysis showed that in approximately half of these families the variants did not completely co-segregate with disease, suggesting that PALB2 acts as a medium-penetrance rather than high-penetrance gene for breast cancer risk." (PMID 24949998, 2014). "This shows a clear role for PALB2 in breast cancer development." (PMID 24949998, 2014). "PALB2 P249L and PALB2 E352Q were each found in one breast cancer case and one control." (PMID 23977390, 2013). "They found that the PALB2 rs249935 G allele was related to a 1.21-fold increased risk of breast cancer for each A allele carried, while rs249954 and rs16940342 had no role in breast cancer risk." (PMID 23318652, 2013). "The search for additional breast cancer susceptibility genes has been of great interest and has successfully led to the identification and characterisation of ATM (MIM#607585), BRIP1 (MIM#605882), CHEK2 (MIM#604373), and PALB2 (MIM#610355)." (PMID 23448497, 2013). "This variant, PALB2 c.2993G>A, has previously been identified in studies examining the role of PALB2 in multiple-case breast cancer families that are not known to carry BRCA1 or BRCA2 mutations." (PMID 23448497, 2013). "This is the case for mutations in the PALB2, BRIP1 and ATM genes, where heterozygotes have an increased lifetime risk of breast cancer, and homozygotes are diagnosed with multisystemic genetic syndromes (Fanconi’s anaemia for the first 2 genes and ataxia-telangiectasia for the latter)." (PMID 23570263, 2013). "PALB2 c.2982_2983insT has previously been identified in one of 923 women from multiple-case breast cancer families screened for PALB2 mutations in a UK study (and not in 1,084 unaffected women)." (PMID 23448497, 2013). "Although inherited PALB2 mutations are associated with increased risks of developing breast cancer, risk to ovarian cancer has not been fully explored in this demographically unique population." (PMID 23302520, 2013). "Most currently known breast cancer predisposition genes play a role in the repair of DNA double-strand breaks by homologous recombination: BRCA1 and BRCA2, associated with a high risk of breast cancer, and BRIP1 and PALB2, associated with a moderate risk." (PMID 24139550, 2013).